SPIN2B (spindlin family member 2B)
Description:
Involved in the regulation of cell cycle progression, this activity is related to the inhibition of apoptosis following the removal of essential growth factors. Exhibits H3K4me3-binding activity.
Synonyms: SPIN-2; SPIN-2B; TDRD26; SPIN2_duplicate; dJ323P24.2
Tractability: Small molecule: a structure with a bound ligand is known; a high-quality ligand is known. PROTAC: ubiquitination databases record sites on it; a small molecule that binds it is known.
Target class: Reader; Epigenetic regulator
Chemical probes: VinSpinIn (high quality)
Gene: Protein-coding gene on chromosome X (57,118,551 to 57,121,840, reverse strand). Ensembl gene ENSG00000186787.
Subcellular location: Nucleus
Subcellular location (Human Protein Atlas): Nucleoplasm
Gene Ontology:
Molecular function: histone H3K4me3 reader activity; protein binding
Biological process: regulation of DNA-templated transcription; chromatin organization; gamete generation
Cellular component: nucleoplasm; nucleus
Homologues: Orthologues: tropical clawed frog spin1 (79% identical), zebrafish spina (72% identical), rat LOC134484257 (62% identical), rat LOC134486234 (61% identical), rat LOC134486240 (60% identical), rat LOC134486221 (57% identical), rat Ssty1-ps5 (54% identical), mouse Gm20737 (53% identical), mouse Gm20772 (53% identical), mouse Gm20773 (53% identical), mouse Gm20777 (53% identical), mouse Gm20807 (53% identical), and 50 more. Paralogues in human: SPIN2A (99% identical), SPIN1 (78% identical), SPIN3 (74% identical), SPIN4 (64% identical).
Diseases named in the same sentence as SPIN2B in open-access papers:
SPIN2B is named in the same sentence as 2 diseases in open-access papers, as found by Europe PMC text mining. Sharing a sentence is not in itself a finding about the gene and the disease.
SPIN2B shares sentences with these, for which no sentence is quoted: adenomyosis (1 paper); Liddle syndrome (1).